EIF4EP3 (eukaryotic translation initiation factor 4E pseudogene 3)
Gene: Processed pseudogene on chromosome 3 (182,460,417 to 182,461,072, reverse strand). Ensembl gene ENSG00000244199.
Diseases named in the same sentence as EIF4EP3 in open-access papers:
EIF4EP3 is named in the same sentence as 1 disease in open-access papers, as found by Europe PMC text mining. Sharing a sentence is not in itself a finding about the gene and the disease.
EIF4EP3 shares sentences with these, for which no sentence is quoted: tumor (1 paper).